STAT5A (signal transducer and activator of transcription 5A)
Diseases named in the same sentence as STAT5A in open-access papers (continued):
Sharing a sentence is not in itself a finding about the gene and the disease.
tumor (continued). "Taken together, these data indicate that mitochondrial STAT5A positively regulates in vitro cell proliferation under hypoxia conditions and in vivo tumor growth." (PMID 34148062, 2021). "Multivariate Cox regression analysis demonstrated that decreased STAT5A expression, together with encapsulation, big tumor size, and high AFP level, was an independent factor associated with RFS and OS." (PMID 33155364, 2021). "In summary, our study identified that miR‐23a was upregulated in HCC, which further inhibited STAT5A expression and promoted tumor growth through activated AKT phosphorylation." (PMID 33155364, 2021). "More importantly, we found that STAT5A was a target of miR‐23a, whose levels significantly decreased in tumor tissues." (PMID 33155364, 2021). "Signal transducer and activator 5a (STAT5A) is a classical transcription factor that plays pivotal roles in various biological processes, including tumor initiation and progression." (PMID 34148062, 2021). "Normal (uninvolved) breast tissues showed elevated protein expression for NMI and STAT5A compared to their matched primary tumor tissues." (PMID 34078871, 2021). "There is an unmet medical need for development of potent orally bioavailable pharmacological inhibitors of Stat5a/b (Stat5) for several different neoplasms." (PMID 33217941, 2020). "Simultaneously, Stat5a and Stat5b have been found to induce the growth of tumor cells, the progression of the cell cycle and metastasis through the deregulation of the expressions of genes related to intrinsic apoptosis." (PMID 32392733, 2020). "Nuclear PKM2 binds to STAT5a, facilitating the transcriptional activation of STAT5a target gene cyclin D1 and tumor growth." (PMID 33292198, 2020). "Key signaling molecules exclusively affected by tumor-priming include MAP2K3, MARCKSL1, STAT5A, and TNFAIP3, which are specifically associated with NK cell cytotoxicity against tumor targets." (PMID 31242243, 2019). "The authors proposed that uSTAT5A stabilizes heterochromatin, thereby suppressing tumor cell growth through epigenetic interaction of STAT5A through a PVVVI motif with HP1α bound to H3K9me." (PMID 29728695, 2018). "A substantial body of work supports the concept that Stat5a/b is highly critical for the viability of human PC cells in vitro and xenograft tumor growth in vivo." (PMID 27741508, 2017). "In TRAMP-derived PC cell lines, use of an inducible carboxy terminal-truncated Stat5a/b construct to inhibit wild-type Stat5a/b activity led to decreased PC cell growth in soft agar and tumor formation in nude mice." (PMID 27741508, 2017). "This study highlights the important role of HCC‐derived exosomal miR‐500a‐3p in intercellular communication, which may be responsible for HSC activation and tumor aggressiveness via the downstream SOCS2/JAK3/STAT5A/STAT5B regulatory loop." (PMID 39574357, 2025). "Thus, a comprehensive study is necessary for understanding JAK2/STAT5A-mediated promotion of VM at tumor microecological level." (PMID 39310105, 2024). "The enrichment of Th2 cells in HCC may be mediated by STAT5A signaling, facilitating tumor growth or metastasis through immunosuppressive cytokines like IL-4 and IL-10." (PMID 38840234, 2024). "Circ_0086722 sponged miR-339-5p, regulating STAT5A to drive tumor progression in PCa." (PMID 39143552, 2024). "Additionally, HE and IHC staining on in situ xenograft tumor specimens were conducted and the morphological characteristics of the circCMTM3/STAT5A/SRSF1 feedback loop were identified." (PMID 39310105, 2024). "From here, we understand the complexity of the cellular response when the JAK/STAT pathway is activated following receptor interaction with different ligands: for example, STAT3 and STAT5A/B are involved in tumor progression, while STAT1 exhibits a tumor-suppressive effect." (PMID 38927059, 2024).
tumor (continued). "Consequently, IL-2 produced by infiltrating lymphocytes stimulates tumor STAT5A signaling, which, in turn, synergizes with TET2 to epigenetically elevate tumor cGAS expression, thereby establishing a positive feedback loop." (PMID 39107856, 2024). "Consequently, we deduced that high expression of STAT1, STAT2, STAT4, and STAT5A indicated low BRCA tumor purity." (PMID 36968603, 2023). "We found that down-regulation of STAT5A could significantly increase the tumor size and tumor weight." (PMID 35517418, 2022). "The influence of STAT5A on tumor growth was measured through establishing transplanted tumor model." (PMID 35517418, 2022). "Also, it has been reported that miR-141 inhibits BC tumor initiation by targeting, two TFs, STAT5A and PR." (PMID 36418345, 2022). "Furthermore, we confirmed that increased miR‐23a promoted glucose metabolism and tumor growth through miR‐23a‐STAT5A‐AKT signaling in HCC." (PMID 33155364, 2021). "More importantly, cells harboring p.V706fs (c.2118_2119delTG) vector had more aggressive growth of p-STAT5A and PD-L1 expression, which might promote tumor immune evasion." (PMID 34051805, 2021). "Furthermore, active STAT5a/b protects antiandrogen-liganded AR from proteasomal degradation, while STAT5a/b knockdown combined with antiandrogen treatment enhances proteasomal degradation of AR followed by suppression of tumor growth." (PMID 34638338, 2021). "STAT5A also acts as a key tumor suppressor by reciprocally inhibiting expression of NPM1‐ALK." (PMID 33155364, 2021). "On the other hand, function roles explored in vitro and in vivo suggested that STAT5A could inhibit tumor growth and migration." (PMID 33155364, 2021). "Thus, our findings provide evidence that loss of STAT5A leads to AKT activation and promotes cellular metabolism and tumor growth in HCC." (PMID 33155364, 2021). "In conclusion, our research demonstrated that GM-CSF potentially triggered the loss of tumor immune surveillance in ENKTL patients and promoted disease progression, which was associated with STAT5A mutations and JAK2 hyperphosphorylation, and then upregulates the expression of PD-L1." (PMID 34051805, 2021). "In our study, we found that STAT5A expression was positively correlated with tumor grade." (PMID 34276757, 2021). "Stable expression of STAT5A in Huh7 cells suppressed glucose metabolism and tumor growth." (PMID 33155364, 2021). "Besides, after constructing siSTAT5A cells in dishes with siRNA for 48 h, similar results were also observed that tumor growth was inhibited significantly by MK2206 compared with the STAT5A knockdown group." (PMID 33155364, 2021). "To evaluate loss of STAT5A accelerates glucose metabolism and HCC via AKT activation, we inhibited AKT phosphorylation by MK2206 when STAT5A was knocked down and measured metabolic flux and tumor growth in vivo." (PMID 33155364, 2021). "Effects of specific STAT5a/b knockdown on cell viability and AR signalling also seem to be dependent on the cellular background of the resistant cells, reflecting the challenges of tumour heterogeneity in therapy treatment of late-stage diseases again." (PMID 32790723, 2020). "Hence, the activation of STAT5a also contributes to the initiation of breast cancer, which is an opposing trend from the tumour-suppressive effects of STAT5." (PMID 32872372, 2020). "Enhanced STAT5A/B activation is achieved by copy number gains, enhanced protein expression, or gain-of-function (GOF) mutations, leading to higher pYSTAT5A/B levels contributing to tumor cell survival and disease progression." (PMID 31690038, 2019). "This might indicate opposing roles, namely tumor-suppressive STAT5A and oncogenic STAT5B, in NPM–ALK-driven ALCL." (PMID 31690038, 2019).
tumor (continued). "In conjunction with promotion of EMT, Stat5a/b induced stem-like properties in PC cells, such as tumor sphere formation and expression of the cancer stem cell marker Bmi1, a core component of Polycomb-Repressive Complex 1 (PRC1), which overrides cellular senescence and promotes self-renewal." (PMID 27741508, 2017). "A prodrug of Stafib-1 was shown to inhibit STAT5b with high selectivity over STAT5a in tumor cells." (PMID 25702814, 2015). "Furthermore, glandular carcinoma cells with higher percentage of ERBB4 also stained for STAT5a (50 to 100%) while tumor cells with squamous cell differentiation, and skeletal and smooth muscle cells stained negative for STAT5a." (PMID 25516216, 2014). "However, whereas the STAT5A substrate phosphorylation by tumor versus normal samples in all of the ADT-naïve patients was low; log2 ratio = 0.7±1.2 (n = 3), it was substantially higher in the early CR patient; log2 ratio = 2.6 (n = 1)." (PMID 23675504, 2013). "A function for Stat5a in tumor initiation may involve proliferative upregulation of cyclin D1 and antiapoptotic effects, for instance, through upregulation of Akt1 or induction of Survivin." (PMID 23036105, 2012). "The present study focused on Stat5a and Stat5b expression in normal and malignant cells, but it will be important in future work to include analyses of expression of Stat5a and Stat5b in stromal tumor cells." (PMID 23036105, 2012). "Importantly, in Tet2 or Stat5a deficiency cells-derived tumors, the combination of VC and anti-PD-L1 had no obvious changes in tumor burdens as compared to single VC or anti-PD-L1 therapy." (PMID 38177099, 2024). "Increased STAT5A/B activation is achieved by gains in copy number, by upregulation of protein expression, or gain-of-function (GOF) mutations, which can lead to a higher phosphorylated form of STAT5A/B levels (pYSTAT5A/B) followed by tumor cell survival and disease progression." (PMID 34281163, 2021). "Overall, these studies illustrate that phosphorylation of S726 may be responsible for STAT5a involvement in evasion of apoptosis, while phosphorylation of S780 is responsible for STAT5a involvement in tumor clonogenicity and establishment of anchorage-independent colonies." (PMID 34188118, 2021). "In tumor tissues, four protective genes (JAK2, IL2RG, EEF1E1, and UBB) showed relatively low expression in the high‐risk group; in contrast, the expression of four risk genes (EPS8, FOXO1, STAT5A, and PAPPA) was more highly in the high‐risk group than that in the low‐risk group." (PMID 34825509, 2021). "Furthermore, we elucidated the action mechanisms of ETS1 as a tumor suppressor not only by directly activating down-stream targets linked with tumor cell proliferation/growth but also trans-activation of other tumor suppressor genes, such as ADAMTS9, TXNIP, STAT5A, and NOTCH1." (PMID 32477936, 2020). "Also, STAT5A has been proved to drive the cell proliferation and tumor growth in PC39." (PMID 32447342, 2020). "Importantly, tumor incidence and tumor latency were similar in parous vs virgin Stat5a−/− mice." (PMID 24381245, 2013). "Low tumor levels of Stat5a but not Stat5b mRNA were associated with poor prognosis." (PMID 23036105, 2012). "Recently it was shown that STAT5a could be epigenetically silenced by the tyrosine kinase NPM1-ALK resulting in the lack of reciprocal inhibition of this oncogenic kinase by STAT5a providing some evidence of a possible tumor suppression function for STAT5a." (PMID 21655368, 2008). "Using RT-PCR, the expression levels of PIP, PIAS3, SOCS3, STAT5A, and STAT5B were verified at the level of mRNA isolated from the tumor’s margin (normal) (n = 40), mastopathy (n = 16), and BC tumor tissue (n = 42)." (PMID 40003884, 2025). "The EOMES GRN, encompassing CD8A, GZMK, STAT5A, CXCR3, and LAG3, integrates cytotoxic effector functions, migratory capacity, and checkpoint regulation—features critical for sustained anti-tumor immunity." (PMID 40520886, 2025).
tumor (continued). "Accordingly, comparative analyses of STAT5A and STAT5B in matched tumor contexts are needed to delineate their overlapping yet functionally distinct roles in cancer biology." (PMID 41301421, 2025). "In parallel, direct comparative analyses of STAT5A and STAT5B within the same tumor types are needed to disentangle their overlapping and divergent functions, ultimately enabling the development of isoform-specific diagnostic tools and therapeutic strategies." (PMID 41301421, 2025). "Based on our results from the tumor and surrounding healthy tissue samples, HIF1A emerged as the primary determinant of EPO, EPOR and JAK2/STAT5A signaling pathway expression in ccRCC." (PMID 40332447, 2025). "Conversely, compared to PD doublets, both CR and PR activated STAT5A and/or STAT5B which can have dual roles as tumour promoting or tumour suppressing TFs48." (PMID 40280979, 2025). "The transcription factor STAT5A further suppresses KLF4 transcription, promoting tumor progression, but KLF4 overexpression can counteract the oncogenic effects of STAT5A." (PMID 39995670, 2025). "Subsequently, circCMTM3/STAT5A/SRSF1 positive feedback loop sustainably enhances VM formation and accelerates tumor progression in GBM." (PMID 39310105, 2024). "While STAT3 has been extensively studied in solid tumors, including GBM, less is known about the role of STAT5A and STAT5B in tumor progression." (PMID 38892466, 2024). "In TCGA database, tumor TET2, STAT5A, and cGAS expressions positively correlated with vascular normalization-associated genes including vascular stabilization, endothelial-lymphocyte interaction, pericytes and T cell chemotaxis." (PMID 38177099, 2024). "Since hepatocyte growth factor (HGF) is the sole ligand for MET and is enriched in the tumor microenvironment, we first evaluated the function of MET on phosphorylating and activating STAT5A with the treatment of HGF in both LNCaP and C42B cells." (PMID 38745318, 2024). "As a result, the level of STAT5A and STAT5B were significantly downregulated in tumor tissues compared with normal tissues (P < .05)." (PMID 36862902, 2023). "On the whole, it was illustrated that higher the expression of STAT1, STAT2, STAT3, STAT4, STAT5A, and STAT5B, the lower the tumor purity." (PMID 36968603, 2023). "The STAT family of transcription factors, which includes STAT1, STAT2, STAT3, STAT4, STAT5a, STAT5b, and STAT6, plays distinct roles in cell differentiation, tissue repair, and anti-tumor response." (PMID 36324680, 2022). "In the greatest number of tumors, STAT4 was correlated with tumor growth, then STAT1, STAT3, STAT6, STAT5B, STAT2, and STAT5A." (PMID 36176415, 2022). "The results showed that the expression of STAT1, STAT2, STAT3, STAT5A, and STAT6 increased with increasing tumor grades." (PMID 34276757, 2021). "Conditional knockouts for STAT3 and STAT5A/B allowed to uncover the effects of STAT3 and STAT5 in T-cell differentiation and memory, dendritic cell function, and NK-cell tumor surveillance." (PMID 34073410, 2021). "STAT3: Among the seven members of the STAT protein family (STAT1, STAT2, STAT3, STAT4, STAT5a, STAT5b, and STAT6), STAT3 and STAT5 are the most important factors for tumor progression." (PMID 34079469, 2021). "To address these issues, we used multiple biochemical and cellular approaches to demonstrate that mitochondrial STAT5A acts as an inhibitor of PDC activity, thereby promoting metabolic remodeling and supporting tumor growth." (PMID 34148062, 2021). "As expected, many DMGs that were hypermethylated and downregulated in CMT including TP63, LIFR, PLA2G16, LRIG1, STAT5A, and AKAP12 and have been known as tumor suppressors, were identified from high scoring (OncoScore > 50) CMT-DMRs." (PMID 32693820, 2020).
tumor (continued). "In support, our immunohistochemical staining of a GBM cohort (n = 45) showed an estimated 5.3-fold (p < 0.001) elevation in STAT3 and STAT5A protein expression in primary and recurrent GBM versus the non-tumor group." (PMID 31783691, 2019). "In NPM-ALK-driven neoplasms, silencing of STAT5B blocks and silencing of STAT5A supports the disease." (PMID 30679796, 2019). "In Tet2-knockdown mice, the outgrowth of TFH-like tumor cells was connected to methylation changes of BCL-6, the locus repressor of STAT5A/B." (PMID 29148847, 2018). "Interestingly, the presence of active Stat5a/b even in one of the 10 tissue cores already predicted likely cancer recurrence after radical prostatectomy, suggesting that those PCs with elevated nuclear Stat5a/b anywhere in the tumor may already have micrometastasized at the time of surgery." (PMID 27741508, 2017). "At the same time, Stat5a/b overexpression in DU145 cells increased colony formation in vitro and accelerated xenograft tumor growth in vivo." (PMID 27741508, 2017). "In the current review, we discuss the hotspots of MLV integration into several genes: c-Myc, Stat5a and N-myc, as well as ZFP521, as examined in tumor genomes." (PMID 27721401, 2017). "Our previous finding demonstrated that SSM2 and SSM3 cells display persistent prolactin receptor signaling with activation of JAK2, STAT3 and STAT5A/5B, and that pharmacological inhibition of pJAK2 increased SSM2 and SSM3 tumor cell apoptosis." (PMID 27391074, 2016). "There was a tendency for greater STAT5A protein expression in tumor tissue compared to surrounding healthy tissue and without statistical significance." (PMID 40332447, 2025). "Additionally, a positive correlation was found between tumor TET2, STAT5A, cGAS expression and intratumoral CD8+ T cell infiltration." (PMID 38177099, 2024). "Based on the epigenetic regulation of tumor cGAS by TET2 synergized with STAT5A signaling, stimulating TET2 activity by VC triggers tumor cGAS-cGAMP-endothelial STING pathway activation and induces tumor vascular normalization, thereby potentiating immunotherapy efficacy." (PMID 38177099, 2024). "Furthermore, HCC patients with high tumor TET2, p-STAT5A, cGAS, LRRC8C, and endothelial STING expression had better clinical outcome." (PMID 38177099, 2024). "The average expression values of STAT1 (p < 0.001), STAT2 (p < 0.001), STAT3 (p < 0.001), STAT4 (p < 0.001), STAT5A (p < 0.001), STAT5B (p < 0.001), and STAT6 (p < 0.001) among immune subtypes C1-C6 in all tumor types were identified to have notable differences." (PMID 36968603, 2023). "Thus, higher the expression of STAT1, STAT2, STAT3, STAT4, STAT5A, and STAT5B, the lower the tumor purity." (PMID 36968603, 2023). "Likewise, the differences in the expression levels of STAT2, STAT3, STAT4, STAT5A, STAT5B, and STAT6 between normal and tumor tissues were also displayed." (PMID 36968603, 2023). "We found that within the tumor epithelium, it was Stat3 and not Stat5 signaling that was most abundant, with little to no detection of Stat5a." (PMID 37164949, 2023). "According to the scores evaluated by the staining‐positive cells, we found that STAT5A expression was sharply reduced in tumor tissues compared with nontumor adjacent tissues." (PMID 33155364, 2021).